TLR3 (toll like receptor 3)
Diseases named in the same sentence as TLR3 in open-access papers (continued):
Sharing a sentence is not in itself a finding about the gene and the disease.
Obesity (continued). "However, another study showed that TLR3 deficiency in mice does not significantly influence HFD-induced obesity and system insulin sensitivity or inflammation." (PMID 31582899, 2019). "In obesity, dying adipocytes may therefore release mRNA, which is then recognized by TLR-3." (PMID 25867514, 2015). "TLR-3 deficiency did not influence HFD-induced obesity, compared to WT mice." (PMID 25867514, 2015). "TLR3 and TLR7 KOs were found to be protective against HFD induced obesity and weight gain and IL1a-KO reduces adiposity, which reflects predicted gene changes in CR20-HFD males compared to FED-HFD." (PMID 38720938, 2023). "Certainly, TLR3 agonists are being explored for their potential to repair the BM niche and direct MSC2 to repair cardiac damage and cardiovascular disease in obesity." (PMID 36105811, 2022). "Thus, although obesity in general may increase TLR3 expression, perinatally-induced obesity may not cause corresponding changes in transport of the ligand into the cell." (PMID 23964195, 2013). "Furthermore, TLR3/TLR7/IRAK1 and TLR3/TLR9 were identified as independent predictors of AT SRA1 expression in individuals with obesity and T2D, respectively." (PMID 36552771, 2022). "Regarding expression of TLRs, their downstream signaling mediators and IRFs, adipose expression of TLR2 (p = 0.018), TLR3 (p = 0.010), TLR8 (p = 0.048), IRAK1 (p = 0.047), and IRF5 (p = 0.016) was significantly higher in participants with obesity compared to NW participants." (PMID 36552771, 2022). "TLR-3-/- and WT animals were exposed to a high-fat diet (HFD) for 16 weeks to induce obesity." (PMID 25867514, 2015). "In line with the results from the animal study that did not reveal a vital role for TLR-3 in mediating obesity-induced inflammation and the development of insulin resistance, the function of the receptor in human adipose tissue appears to be relatively small." (PMID 25867514, 2015). "Nevertheless, in mice after 16 weeks of HFD and in humans, the data does not support a fundamental role for TLR-3 in the development of obesity-induced adipose tissue inflammation and insulin resistance." (PMID 25867514, 2015). "However, TLR3 signaling had no influence on the obesity-induced inflammation in adipose tissue in vivo." (PMID 32708964, 2020). "Multiple TLRs, including TLR2, TLR3, TLR4, TLR5, TLR8, TLR9, and TLR10, have been indicated in the regulation of PAMPs from gut microbiota and DAMPs from metabolic stress and tissue damage, which initiate the inflammatory responses contributing to the development of obesity-related chronic diseases." (PMID 31582899, 2019). "However, in spite of its high expression levels in human adipocytes that may suggest otherwise, our results do not provide evidence for a vital, important role of TLR-3 in adipose tissue during diet-induced obesity." (PMID 25867514, 2015). "The second key difference between immune dysfunction as a result of perinatal obesity and that of diet-induced obesity in adulthood is that perinatal obesity leads to an exacerbated immune response to a TLR4-mediated challenge, but not to a TLR3-mediated one." (PMID 23964195, 2013). "When assessing the placental expression of factors related to viral recognition (TLR3, TLR7, and IRF3) and antiviral response (IFNs I and III, STING, RIG-I, MxA, and ISG15) from parturient with pregestational obesity (BMI ≥ 25), no changes were detected between the obese and non-obese samples." (PMID 36851534, 2023).
pancreatic cancer (16 papers, 2015 to 2025). "Curcumin plays a significant role in inhibiting chronic inflammation and pro-inflammatory factors associated with pancreatic cancer by regulating TLR3 and its downstream signaling pathways." (PMID 40535567, 2025). "These nine kinases were silenced respectively in Panc1 and Cfpac pancreatic cancer cells, and then nuclear translocation of TLR3 in cancer cells was evaluated." (PMID 40675966, 2025). "To reinforce the roles of c-Myc/PRMT5 as downstream effectors, we used c-Myc inhibitor or PRMT5 inhibitor for in vivo treatment in the pancreatic cancer liver metastasis model bearing TLR3 knockout cancer cells with NLS-TLR3 rescue." (PMID 40675966, 2025). "To clarify the in vivo functions of nuclear TLR3, we constructed a tumor-bearing mouse model with pancreatic cancer liver metastasis." (PMID 40675966, 2025). "Although we verified our observations in clinical samples from pancreatic cancer and several other cancers, more types of cancers are required to verify the pro-tumoral functions of nuclear TLR3 in pan-cancer research." (PMID 40675966, 2025). "Immunohistochemistry analysis confirmed TLR3 nuclear localization in pancreatic cancer, as well as colon cancer, gastric cancer and lung adenocarcinoma samples." (PMID 40675966, 2025). "More importantly, we first confirmed the oncogenic competency of TLR3, a core regulator in pyroptosis, in pancreatic cancer (PC) development through experiments in vitro." (PMID 35000541, 2022). "TLR3 possesses promoting effects on proliferation, migration, and invasion of pancreatic cancer cells." (PMID 35000541, 2022). "TLR3 was significantly upregulated in pancreatic cancer (PC) cells (BxPC-3 and PANC1) compared to normal pancreatic duct epithelia cell (HPDE6-C7)." (PMID 35000541, 2022). "Rintatolimod upregulated the expression of TLR3 in pancreatic cancer cells about 7 times more than the expression in untreated cells." (PMID 34207861, 2021). "To further confirm above results, we separated the cytoplasmic and nuclear protein fractions of cancer cells, and found that TLR3 was highly expressed in the cytoplasm and nucleus, especially in the nucleus of pancreatic cancer cells, as compared to that in corresponding normal cells." (PMID 40675966, 2025). "Furthermore, we performed immunohistochemical staining to detect TLR3 expression in primary and corresponding metastatic lesions from 45 pancreatic cancer patients." (PMID 40675966, 2025). "Besides, c-Myc inhibitor and PRMT5 inhibitor both suppressed the metastasis induced by TLR3 rescue in the pancreatic cancer liver metastasis model bearing TLR3 knockout cancer cells, reinforcing the non-redundant role of c-Myc/PRMT5 as downstream effectors." (PMID 40675966, 2025). "TLR3 may play a promoting role in the early stages of pancreatic cancer development by inducing inflammatory responses that activate secretion of pro-inflammatory factors, thereby stimulating growth of tumor cells." (PMID 40535567, 2025). "Therefore, during the progression of pancreatic cancer, TLR3 acts as a double-edged sword, serving as part of the immune system’s defense while potentially accelerating the malignant transformation of tumors due to chronic inflammation." (PMID 40535567, 2025). "Furthermore, we employed pancreatic cancer tissue microarrays to analyze the expression patterns of TLR3, PRMT5 and c-Myc." (PMID 40675966, 2025). "TLR3 promotes proliferation, migration, and invasion of pancreatic cancer cells." (PMID 35000541, 2022). "Finally, the biofunctions of toll like receptor 3 (TLR3) in pancreatic cancer (PC) cells were investigated through qPCR, MTT, colony formation, and Transwell assays." (PMID 35000541, 2022). "Previous evidence demonstrated the interplay between TLR3 and Wnt5a signaling in pancreatic cancer." (PMID 34884547, 2021). "However, despite TLR3 expression in PC cells, it is still unclear which role it plays in pancreatic cancer pathophysiology." (PMID 34884547, 2021).
pancreatic cancer (continued). "We found that Gemcitabine (GEM), a first-line chemotherapeutic drug broadly applied in pancreatic cancer treatment, could lead to a dose-dependent increase in TLR3 expression, as well as increased nuclear levels of TLR3 in Panc1 and Cfpac pancreatic cancer cells." (PMID 40675966, 2025). "Clinically, we found the co-localization of TLR3, PRMT5 and c-Myc within the nuclei of cancer cells presented in tumor tissue sections obtained from pancreatic cancer patients undergoing neoadjuvant chemotherapy." (PMID 40675966, 2025). "Additionally, high levels of TLR3, PRMT5 and c-Myc transcripts were correlated with reduced survival rates in pancreatic cancer patients." (PMID 40675966, 2025). "Therefore, we explored the effect of Rintatolimod (Ampligen®) (AIM ImmunoTech, Ocala, FL, USA), a Toll-like receptor 3 (TLR3) agonist, to treat uninfected human pancreatic cancer cells (HPACs)." (PMID 34207861, 2021). "Thus, we posit that DC-based immunotherapy, in conjunction with toll-like receptor (TLR)-3 agonist poly-ICLC, is a promising approach for harnessing immunity against metastatic or locally advanced unresectable pancreatic cancer (PC)." (PMID 28388966, 2017). "Similarly, although it was reported that HIF-1 could up-regulate TLR4 expression in pancreatic cancer cells under hypoxic conditions, to our knowledge this is the first report that HIF-1 can upregulate TLR3 and TLR4 in OSCC cell lines under hypoxia." (PMID 27191981, 2016). "Additionally, using a separate cohort of 74 pancreatic cancer patients who underwent neoadjuvant chemotherapy prior to surgical resection, we found that patients with a high tumor regression grade (TRG) showed a significantly increased nuclear TLR3 expression in cancer cells." (PMID 40675966, 2025).
Rotavirus infection (16 papers, 2011 to 2025). Infection with any of the rotaviruses. "Decreased TLR3 expression in the intestinal epithelium has shown evidence of age-dependent susceptibility to rotavirus infection." (PMID 40732672, 2025). "Together, these data confirm the age-dependent susceptibility towards rotavirus infection and show that rotavirus susceptibility correlates with low expression of Tlr3 and responsiveness in intestinal epithelial cells." (PMID 22570612, 2012). "Our results identify the postnatal increase in the intestinal epithelial expression of Tlr3 as a key factor determining the age-dependent susceptibility to rotavirus infection." (PMID 22570612, 2012). "We thus conclude that the low intestinal epithelial Tlr3 expression contributes to the age-dependent susceptibility towards rotavirus infection." (PMID 22570612, 2012). "Furthermore, it was reported that adult mice deficient in TLR3 or its adaptor molecule TRIF are highly susceptible to rotavirus infection than wild-type mice." (PMID 34163470, 2021). "Furthermore, it was reported that adult mice deficient in TLR3 are highly susceptible to rotavirus infection compared with wild-type animals." (PMID 34946051, 2021). "Interestingly, epithelial TLR3 expression inversely correlated to rotavirus infection, suggesting insufficient epithelial TLR3 expression in neonates may underlie their unique susceptibility to this pathogen." (PMID 36090061, 2022). "Thus, upregulation of epithelial TLR3 expression during infancy might contribute to the age-dependent susceptibility to rotavirus infection." (PMID 22570612, 2012). "Both strains improved IFN-β, IFN-λ and antiviral factors expression in PIE cells after TLR3 activation, which correlated with an enhanced resistance to rotavirus infection." (PMID 34163470, 2021). "TLR3 is an essential receptor that initiates an antiviral response in human IECs upon rotavirus infections." (PMID 33203755, 2020). "Rotavirus has been shown to induce signaling through TLR3, and villous pathology similar to that observed in rotavirus infection can be induced by intraluminal injection of Poly I:C." (PMID 26414184, 2015). "Strikingly, expression of one such immune receptor, Toll-like receptor 3 (Tlr3), precisely correlated with the establishment of resistance against rotavirus infection in mice." (PMID 22570612, 2012). "In conclusion, we describe an age-dependent upregulation of intestinal epithelial Tlr3 expression during the postnatal period and demonstrate its functional relevance in an oral rotavirus infection model." (PMID 22570612, 2012). "Next, we investigated the role of Tlr3- and Trif-mediated signaling for rotavirus recognition and antiviral host defense in the context of both neonatal and adult rotavirus infection." (PMID 22570612, 2012). "Using an oral rotavirus infection model, we confirmed that Tlr3-induced immune responses contributed to restrict rotavirus replication in adult but not neonate animals." (PMID 22570612, 2012). "The time course of increasing epithelial Tlr3 expression during the postnatal period precisely correlated with the establishment of resistance against symptomatic rotavirus infection." (PMID 22570612, 2012). "The significance of enhanced Tlr3/Trif-mediated Ifn-λ expression is illustrated by the recently reported protective effect of Ifn-λ during rotavirus infection." (PMID 22570612, 2012). "In addition, our transcriptional studies performed in intestinal epithelial cells cultures revealed the strain-dependent capacity of lactobacilli to modulate the TLR3-mediated antiviral immune response and the resistance to rotavirus infection." (PMID 34578229, 2021). "Research has demonstrated that TLR3 has a key role in the outcome of rotavirus infection." (PMID 34946051, 2021).
Rotavirus infection (continued). "Interestingly, analysis of human duodenal biopsies revealed a significantly enhanced TLR3 expression in children of 5 years and older, correlating with the enhanced resistance to rotavirus infection in this age group." (PMID 22570612, 2012). "Rotavirus recognition by PRRs may be cell type-specific, and other endosomal or surface membrane-associated PRRs such as TLR3, TLR7, and TLR9 have been implicated in stimulating innate responses to rotavirus infection, although more definitive studies on these topics are required." (PMID 23359266, 2013). "Rotavirus infection triggers the production of IL-8, IL-6, and TNF-α in IECs by activating the TLR3 and RIG-I pathways." (PMID 32038538, 2019). "We have demonstrated that L. delbrueckii TUA4408L and its EPS are capable to regulate the innate immune response induced by the activation of TLR3 and improve the resistance of PIE cells against rotavirus infection." (PMID 30319634, 2018). "Our results showed that PIE cells have functional TLR3, RIG-I, and MDA-5 receptors, which are able to detect rotavirus infection and enhance the expression of IFN-β and the ISGs MxA and RNase L, which are important antiviral effectors of IFN pathway." (PMID 28210256, 2017). "Based on the strong epithelial cell tropism of rotavirus and the established role of dsRNA in Tlr3 stimulation, we hypothesized that age-dependent differences in epithelial innate immune recognition might contribute to the protection of adult mice from symptomatic rotavirus infection." (PMID 22570612, 2012). "Two strains with a remarkable immunomodulatory potential were selected, L. salivarius FFIG35 and FFIG58, and their capacities to differentially modulate TLR3-triggered innate immune response in PIE cells, as well as the resistance to rotavirus infection were evaluated in detail." (PMID 34163470, 2021). "Taking into consideration that L. salivarius FFIG58 and FFIG35 had a remarkable ability to modulate the innate immune response triggered by TLR3 in PIE cells, we aimed to evaluate whether these strains conferred protection against rotavirus infection." (PMID 34163470, 2021). "Further studies are clearly needed to evaluate the role of TLR3 in rotavirus infection, particularly in the primary target, the non-adult host." (PMID 23359266, 2013). "Rotavirus infection of adult bone marrow chimeric mice clearly demonstrated the protective role of signaling via the Tlr3 adaptor molecule Trif in non-hematopoietic cells." (PMID 22570612, 2012). "Rotavirus infection-induced IFN-β secretion and interferon stimulated response element (ISRE) activation were impaired by silencing RIG-I, but not by silencing toll-like receptor 3 (TLR3) or protein kinase R (PKR)." (PMID 22152002, 2011).
HCMV infection (15 papers, 2007 to 2025). "Tabeta and colleagues reported that during mouse cytomegalovirus infection deficiency of TLR3 and TLR9 increases the infection due to reduced type I IFN secretion and NK cell activation." (PMID 25539593, 2014). "Adding to the viral-induced immunosuppressive effects, higher PD-L1 levels are associated with HCMV in tumour specimens, and HCMV infection in vitro induces PD-L1 expression through toll-like receptor 3 (TLR3) regulation in glioblastoma, and this may promote a more malignant phenotype." (PMID 41194660, 2025). "It should also be noted that scrambled siRNA slightly increased cFLIPL abundance, possibly through recognition by TLR3, which reduced the magnitude of cFLIPL induction following HCMV infection." (PMID 41190811, 2025). "They reported an increase in the frequency of heterozygous TLR3 rs3775291 genotypes in children with HCMV infection in comparison to uninfected controls." (PMID 32578708, 2020). "Nevertheless, TLR3 has no function in the innate/early phases of the cellular response to HCMV in human Mo-DCs, as recently demonstrated by experiments in which TLR3 was silenced before HCMV infection." (PMID 22701276, 2012). "HCMV infection initiates necroptosis signaling through the combined effects of cFLIPL and TLR3." (PMID 41190811, 2025). "Regardless, TLR3 is critical to the early activation of RIPK3 following HCMV infection, yet it remains unclear how TLR3 signaling is triggered following infection." (PMID 41190811, 2025). "Thus, TLR3 appears to respond to HCMV infection by increasing both RIPK3 protein abundance and phosphorylation levels in order to initiate the necroptotic pathway within infected monocytes." (PMID 41190811, 2025). "For example, TLR3-induced necroptosis in fibroblasts and endothelial cells did not require RIPK1 but involved both RIPK3 and MLKL, whilst necroptosis due to cytomegalovirus infection was RIPK1-independent but involved RIPK3 activity." (PMID 33925729, 2021). "Other studies also showed the SNPs located in TLR2, as well as in TLR3, TLR4, TLR7 and TLR9 genes, to be contributing to HCMV infection." (PMID 28118851, 2017). "In human acute monocytic leukemia cell line THP1 and in foreskin fibroblast cell lines, HCMV infection induces the expression of TLR2, TLR3 and TLR9 genes." (PMID 28118851, 2017). "HCMV infection in fibroblasts is also influenced by the TLR3 and TLR4 pathways; stimulation of fibroblasts with TLR3 and TLR4 ligands inhibits viral replication through an IFN-β-dependent mechanism." (PMID 22701276, 2012). "Recently, HCMV infection has been shown to result in upregulation of TLR2, TLR3, and TLR9 in monocytes in the presence of the human monocyte scavenger receptor A type 1 (SR-A1)." (PMID 23061052, 2012). "However, other studies showed some role of SNPs in TLR2, TLR3, TLR4, TLR7 and TLR9 genes in HCMV infections." (PMID 25844529, 2015). "TLR3 and TLR9 levels were increased after 1 hr of HCMV infection." (PMID 23061052, 2012). "Regardless of the mechanism of TLR3 activation, our study demonstrates that the concomitant increase in cFLIPL levels and signaling from TLR3 are necessary to trigger the early steps of the necroptotic cascade following HCMV infection of monocytes." (PMID 41190811, 2025). "cFLIPL-mediated inhibition of caspase-8 and the simultaneous activation of TLR3, but not TNFR1 or TLR4, is required for RIPK3 activation following HCMV infection of monocytes." (PMID 41190811, 2025). "The expression of TLR3 and TLR4 was significantly downregulated during wild-type HCMV infection, but not during infection by mutant HCMV with a deletion of the US7-US16 region." (PMID 31604943, 2019). "Mice lacking TLR3 display reduced IFN-α/β production and an increased viral load against mouse cytomegalovirus infection." (PMID 21637773, 2011). "In our in vitro studies, no NK cells were present in HFF cultures showing that TLR3- and TLR4-ligands had a direct effect on the HCMV infection targets." (PMID 18053251, 2007).